CD1D (CD1d molecule)
Diseases named in the same sentence as CD1D in open-access papers (continued):
Sharing a sentence is not in itself a finding about the gene and the disease.
Autoimmunity (continued). "The high conservation between human and mouse CD1d, and CD1d-restricted NKT cells, and their strong cytokine mediated immunomodulatory effects, has prompted studies investigating NKT cell directed therapy in various immune settings ranging from autoimmunity to tumor immunity." (PMID 30881361, 2019). "The proposed model of GPI-directed immune attack needs to account for the tissue specificity of autoimmunity in AA, despite the ubiquitous presence of GPI and the broad expression of CD1d on non-hematopoietic tissues." (PMID 35154088, 2021). "Many researchers utilize mice for immunological studies; however, mice only express CD1d and do not express group 1 CD1 molecules, limiting the ability to study CD1-restricted T cells in the context of autoimmunity." (PMID 30061888, 2018). "Moreover, the presence and relative amounts of CD1d-restricted T cells did not correlate with the presence and size of PNH clones, as would have been expected if CD1d-mediated autoimmunity was responsible for PNH immune selection." (PMID 35154088, 2021).
Insulin resistance (13 papers, 2011 to 2024). Increased resistance towards insulin, that is, diminished effectiveness of insulin in reducing blood glucose levels. "Steroid administration in CD1d−/− mice was associated with significant insulin resistance manifested by increased fasting serum glucose levels and increased GTT, along with hypertriglyceridemia." (PMID 35392825, 2022). "Further, adipocyte-specific CD1d deficiency ameliorated high fat diet-induced obesity and insulin resistance." (PMID 30061888, 2018). "In conclusion, we have found that CD1d−/− mice have mildly exacerbated hepatic triglyceride accumulation associated with hepatic insulin resistance when fed a steatogenic diet." (PMID 21980475, 2011). "HFD can induce a reduction in the expression of CD1d molecules on the surface of AT-M2s, and also cause a change in APCs from M2s to M1s, whereas iNKT cell activation by M1s exacerbate metaflammation and insulin resistance by promoting Th1 responses and inhibiting M2 polarization." (PMID 34421909, 2021). "In contrast, other reports have shown that a similar conditional knockout mouse, adipocyte-specific CD1d-KO (CD1dADKO), exhibited reduced IL-4 expression in adipose iNKT cells, resulting in aggravated AT inflammation and insulin resistance in HFD-fed mice." (PMID 38426085, 2024). "Critically, the ablation of CD1d specifically on adipocytes resulted in inflammation and insulin resistance, indicating an adipocyte-intrinsic role for CD1d." (PMID 34837070, 2022). "The increases of PGC-1 and SCD-1 are consistent with an insulin resistant phenotype in the liver and correlate with the more severe insulin resistance observed in CD1d−/− mice following HFD feeding." (PMID 24465369, 2014). "Consistent with our metabolic data showing insulin resistance, the levels of IL-6 in the liver and adipose tissue were higher in CD1d−/− mice than WT mice." (PMID 24465369, 2014). "Insulin tolerance testing (ITT) revealed a significantly greater fasting glucose levels in CD1d−/− mice compared to WT mice, a common phenotype seen in diabetic animals and patients with insulin resistance." (PMID 24465369, 2014). "After 20 weeks of HFD feeding, CD1d−/− and WT mice were tested for insulin resistance and glucose tolerance." (PMID 24465369, 2014). "This suggested that the mild exacerbation of insulin resistance in CD1d−/− mice was due to hepatic insulin resistance." (PMID 21980475, 2011). "Our study established a model of NAFLD and metabolic derangements by steroid administration for eight weeks in which the steroid-mediated steatosis was CD1d-dependent while steroid-induced liver necrosis and inflammation, insulin resistance, and hyperlipidemia were CD1d-independent." (PMID 35392825, 2022). "HFD-fed adipocyte-specific CD1d-knockout mice showed severely reduced numbers of iNKT cells in adipose tissues and decreased responses to α-GalCer-induced iNKT activation, which finally aggravates adipose tissue inflammation and insulin resistance." (PMID 34421909, 2021). "Recent studies have shown that CD1d expression and iNKT cell numbers decrease in obese humans and mice, leading to increased recruitment of proinflammatory macrophages in adipose tissues and insulin resistance." (PMID 30061888, 2018). "Thus, it is possible that compared with CD1d−/− -Balb/c mice, the CD1d−/− -C57B6mice develop a more severe phenotype with not only worsened insulin resistance but also increased M1-mediated inflammation." (PMID 24465369, 2014). "Although indistinguishable from littermates on a chow diet, CD1d−/− mice develop slightly exacerbated insulin resistance on a high fat diet." (PMID 21980475, 2011). "Furthermore, the degree of insulin resistance, glucose intolerance, liver steatosis, and adipose and liver inflammatory marker expression (TNFα, IL-6, IL-10, IFN-γ, MCP-1, MIP1α) induced by high fat feeding in CD1d−/− were not different from WT." (PMID 21674035, 2011).
atherosclerosis (12 papers, 2012 to 2024). A disease characterized by the build-up of fatty material and calcium deposition in the arterial wall resulting in partial or complete occlusion of the arterial lumen. "This argues that, at least at this arterial site, CD1d-restricted or expressing cells other than iNKT cells play an overall proatherogenic role and in their absence, progression of atherosclerosis is slowed." (PMID 31540125, 2019). "We demonstrate that variations in NKT cell populations or other CD1d expressing cells influence plasma lipids and lipoproteins and selectively affect atherosclerosis at three vascular sites in a site and time dependent fashion." (PMID 31540125, 2019). "In fact, it has been reported that the activation of CD1d-restricted iNKT cells exacerbates atherosclerosis." (PMID 28166809, 2017). "The increased titer of atheroprotective E06 NAbs in Cd1d−/− mice may also have contributed to the decreased atherosclerosis." (PMID 32635160, 2020). "The global absence of Cd1d in mouse models of atherosclerosis is associated with a reduction in atherosclerosis." (PMID 32635160, 2020). "The CD1d influence on atherosclerosis and lipid metabolism may be a consequence of CD1d expression on parenchymal cells, such as liver or intestinal cells." (PMID 31540125, 2019). "In addition, it has recently been shown that disruption of the interaction of CD1d on mast cells with NKT cells aggravates atherosclerosis." (PMID 31540125, 2019). "However, as the lesions matured and grew in size, the anti-atherogenic effect of the absence of both NKT cell subsets and other CD1d expressing cells on atherosclerosis at the aortic root was loss and led to increased atherosclerosis at the ascending aortic arch." (PMID 31540125, 2019). "In early atherosclerosis, dendritic cells exclusively overexpress HSP70 as well as HLA-DR and CD1d, the latter being a unique molecule used in lipid antigen presentation." (PMID 23304456, 2012). "In summary, these studies reveal that iNKT and other CD1d-expressing or CD1d restricted cells, which include type II NKT cells impact lipid and lipoprotein levels and the initiation and progression of atherosclerosis in a complex site-specific manner and in some cases gender specific manner." (PMID 31540125, 2019). "As with iNKT cells, the absence of all CD1d-restricted and expressing cells in the CD1d−/− mice exerts a site-specific effect on atherosclerosis." (PMID 31540125, 2019).
breast carcinoma (12 papers, 2011 to 2026). "CD1d1 and CD1d2 co-encode the CD1d protein, which is critical for developing natural killer T cells, and downregulation of CD1d promotes breast cancer metastasis." (PMID 40227606, 2025). "The role of CD1d-restricted type I vs. type II NKT cells in breast cancer has only been addressed using the CD1d-deficient 4T1 mammary carcinoma model." (PMID 21695190, 2011). "We collected conditioned medium, cell-free culture supernatant as previously reported, from human (MCF-7) and mouse (E0771 and 410.4) breast cancer cell lines, and used the medium to treat CD1d-expressing cells (LCD1dwt)." (PMID 39596374, 2024). "NKT cells have been reported to recognize gangliosides in the context of CD1d, and breast cancer cells have been shown to overexpress GD3." (PMID 39596374, 2024). "In order to assess the relevance of these findings to human breast cancer, we analyzed the expression of CD1d in several human mammary cell lines of increasing metastatic potential by RT-PCR." (PMID 21695190, 2011). "In order to assess the importance of CD1d downregulation in human breast cancer, we analyzed a panel of human mammary epithelial cell lines of increasing metastatic potential by RT-PCR for their expression of CD1d." (PMID 21695190, 2011). "In our mouse model of breast cancer metastasis, we detected a significant downregulation of CD1d in the highly metastatic TM40D-MB cells, as compared to the low-metastatic TM40D cells." (PMID 21695190, 2011). "Next we sought to determine the role of tumor-specific CD1d downregulation, in contrast to systemic CD1d inhibition by antibody blockade, in promoting spontaneous breast cancer metastasis." (PMID 21695190, 2011). "In this study, we provide the first evidence that in human breast cancer cells, downregulation of CD1d expression is correlated with increasing metastatic potential." (PMID 21695190, 2011). "Moreover, a murine study with breast cancer cells showed that a downregulation of CD1d results in inhibition of iNKT-related antitumor immunity and promotion of metastasis." (PMID 32973759, 2020). "Downregulation of CD1d in highly metastatic breast cancer cells may similarly enable evasion of immune surveillance and facilitate metastatic progression." (PMID 21695190, 2011). "In this study, we demonstrated that enriched iNKT cells are preferentially cytotoxic to breast cancer cells with increased CD1d expression in vitro, and this effect could be partially abrogated by the addition of anti-CD1d blocking antibody." (PMID 21695190, 2011). "We hypothesize that breast cancer cells, through downregulation of CD1d and subsequent evasion of NKT-mediated antitumor immunity, gain increased potential for metastatic tumor progression." (PMID 21695190, 2011). "To date, no study has directly linked CD1d expression by breast cancer cells and iNKT-mediated antitumor immunity in preventing breast cancer metastasis." (PMID 21695190, 2011). "Rather, the CD1d expression status of the tumor and the stage of disease progression may be important considerations in tailoring future breast cancer immunotherapies that effectively promote iNKT-mediated antitumor immunity." (PMID 21695190, 2011). "We hypothesize that downregulation of CD1d in breast cancer cells may inhibit iNKT-regulated primary and secondary immune responses." (PMID 21695190, 2011). "Based on our in vitro findings, we hypothesized that in vivo blockade of CD1d using an anti-CD1d blocking antibody would inhibit iNKT-mediated antitumor immunity and result in increased breast cancer metastasis." (PMID 21695190, 2011). "We found that pretreatment of breast cancer cells with Migulstat (N-butyldeoxynojirimycin), a drug that blocks the synthesis of GD3, restores CD1d-mediated NKT cell activation." (PMID 39596374, 2024). "Activated NK T cells also recognize CD1d expressed by breast cancer cells and recruit NK cells by releasing IFN-γ, which kills breast cancer cells directly." (PMID 33234169, 2020).
breast carcinoma (continued). "However, the ability of iNKT cells to induce direct cytolysis of CD1d-expressing breast cancer cells has not been reported." (PMID 21695190, 2011). "While CD1d is abundantly expressed by immune cells and tumor cells in the PyMT model (data not shown), production of a stimulatory type I NKT lipid antigen in mammary carcinoma is not described." (PMID 29518903, 2018). "The target cells consisted of two breast cancer cellular lines, MDA-MB468 and SK-BR3, which were analyzed in terms of differential target molecule (EGFR) expression, as well as the presence of non-specific (MICA/B) and specific (CD1d) activating and inhibitory molecules (Fas)." (PMID 40002679, 2025).
B cell lymphoma (11 papers, 2010 to 2025). "NGcGM3 stimulated NKT cell activation via CD1d presentation on B cells, making it an interesting target for CD1d+ B cell lymphomas." (PMID 37908366, 2023). "Type II NKT cells were also shown to suppress immunity against CD1d-transfected B cell lymphoma; amounts of IL-13, TGF-β, and MDSCs correlated with immune suppression." (PMID 25389427, 2014). "In mouse CD1d– ATA B cell lymphoma, we observed reduced LEF-1 and increased IL-6 and Arid5a." (PMID 36050343, 2022). "When CD1d deficiency abrogated NKT2-B1a cell interactions and B1 B cell lymphoma strongly increased in these animals, one reason may be the Cdkn2a gene difference in the BALB/c background, which has the potential to strongly promote B1 B cell growth." (PMID 36050343, 2022). "The strong ATA B cell lymphoma stages in mice were CD1d–, LEF-1–, and IL-6+ with increased Arid5a." (PMID 36050343, 2022). "At saturating conditions, both mAbs bound mouse CD1d1 and rat CD1d expressed at the cell surface equally well, i.e. irrespectively of whether they had been expressed by a transduced human B cell lymphoma, thymocytes or other lymphoid cells." (PMID 20927351, 2010). "Cloned CD1d-mIgG1-HC constructs were used for transfection of rat β2-microglobulin transduced J558L mouse B cell lymphoma cells lacking Ig heavy chain expression but capable of producing mouse Ig lambda light chain as well as mouse β2-microglobulin." (PMID 26599805, 2015). "As antibody blockade of CD1d-expressing tumors would similarly abrogate direct type II NKT recruitment, our TM40D cells may not be able to recruit type II NKT cells, as suggested in the B cell lymphoma study." (PMID 21695190, 2011).
Hepatitis (11 papers, 2008 to 2023). Inflammation of the liver. "Previous studies have demonstrated the critical contribution of NKT cells to ConA-induced hepatitis by showing that CD1d deficient mice were highly resistant to ConA injection compared to wt mice." (PMID 28330461, 2017). "The CD1d KO (NKT deficient) mice showed hepatoprotection against poly(I:C)-induced hepatitis in association with increased number of IL-33 expressing hepatocytes in CD1d KO mice than WT controls." (PMID 24058536, 2013). "This study suggested that enterogenous bacterial glycolipids are important NKT cell agonist, and such antigens are presented by CD1d to activate NKT cells during ConA-induced hepatitis." (PMID 27821872, 2016). "Likewise, serum levels of alanine aminotransferase (ALT) and aspartate aminotransferase (AST) were markedly lower in ConA-treated CD1d−/− mice compared to their WT counterpart, implying that ConA-induced hepatitis was iNKT cell-dependent." (PMID 31850305, 2019). "While several viruses, including vaccinia, herpes simplex, hepatitis, and lymphocytic choriomeningitis viruses decrease CD1d expression in myeloid cells, infections with Salmonella typhimurium or E. coli increase the plasma membrane display of CD1d." (PMID 24904574, 2014). "To assess whether the activation status of DCs was altered in the absence of CD160, we measured the levels of multiple ligands on DCs, including CD1d, CD40, CD80, CD95, PD-L1, and HVEM, during α-GalCer-induced hepatitis." (PMID 31332204, 2019). "Remarkably, αGalCer/CD1d-NPs were also able to rapidly restore and stably maintain normoglycemia in spontaneously diabetic NOD mice for many weeks post-treatment withdrawal, despite the fact that these mice do not have liver inflammation." (PMID 35672409, 2022).
neuroblastoma (10 papers, 2010 to 2025). Neuroblastoma (NB) is the most common solid, extracranial childhood tumor. "NKTs actively traffic to neuroblastoma tissues and destroy CD1d-positive, cancer supporting tumor-associated macrophages (TAMs), and the presence of NKTs in neuroblastoma is associated with improved outcomes." (PMID 28154831, 2017). "iNKT cells have been demonstrated to co-localise with CD1d-expressing TAMs in neuroblastoma and kill TAMs in a CD1d-restricted manner." (PMID 37153585, 2023). "CD1d-dependent killing of growth-promoting TAMs via iNKT cells decelerated tumor growth in a NOD/SCID human neuroblastoma xenograft model." (PMID 28596767, 2017). "Type I NKT cells were found to co-localize with CD1d-expressing TAMs in neuroblastoma and kill TAMs in an IL-15 and CD1d-restricted manner." (PMID 29018445, 2017). "The generated CAR-NKTs can destroy both GD2-positive neuroblasts and CD1d-positive TAMs resulting in a potent antitumor effect in an aggressive metastatic neuroblastoma model in humanized mice." (PMID 28154831, 2017). "Primary human neuroblastoma cells are CD1d−, however, the tumor neuroblastoma microenvironment is highly enriched for CD68+/CD1d+ TAMs, which aliment tumor growth mainly through secretion of IL-6." (PMID 28596767, 2017). "Interestingly, TAMs in the neuroblastoma tumor microenvironment are CD1d-positive, and transferring activated NK T cells led to increased cell death of TAMs in a CD1d-restricted manner and decreased tumor proliferation in vivo." (PMID 32983125, 2020). "Interestingly, in this context, human iNKT cells can kill macrophages that are supposed to infiltrate human neuroblastoma in a CD1d-dependent manner, providing a mechanistic link between neuroblastoma infiltration by iNKT cells and an improved prognosis." (PMID 20072624, 2010). "Indeed, CAR-iNKT targeted both GD2+ neuroblastoma cells and CD1d+ TAMs." (PMID 37153585, 2023). "In addition, Dr. Metelitsa’s group investigated tumor associated macrophages (TAMs) in neuroblastoma and found that while CD1d+TAMs can promote tumor growth, TAMs can also present neuroblastoma antigens that can lead to their recognition and killing by NKT cells." (PMID 34072042, 2021). "However, high expression of CD1d is not always associated with iNKT infiltration, as shown by Metelitsa and colleagues in neuroblastoma samples." (PMID 32973759, 2020). "In preclinical neuroblastoma models, iNKT eliminate CD1d-expressing TAM and inhibit the function of myeloid-derived suppressor cells (MDSC) in a CD1d- and CD40-dependent manner, thereby creating a more favorable microenvironment for effector immune responses." (PMID 40718496, 2025). "In a xenograft human neuroblastoma model in NOD/SCID mice, adoptively transferred type I NKT cells selectively killed TAMs by recognizing CD1d to indirectly control tumor growth." (PMID 30158927, 2018). "In a primary neuroblastoma without MYC-N amplification, CD1d-expressing CD68+ tumor-associated macrophages (TAMs) stimulate tumor growth through production of IL-6, and a high TAM gene signature is associated with poor prognosis." (PMID 30158927, 2018).